TNF (tumor necrosis factor)
Diseases named in the same sentence as TNF in open-access papers (continued):
Sharing a sentence is not in itself a finding about the gene and the disease.
Salmonella Infections (continued). "Typically Salmonella infects thirty-forty percent of IECs in culture models of infection, however, we and others have found that Salmonella infection activates NF-κB DNA binding activity to levels equivalent to that of TNFα which activates NF-κB in all of the cells." (PMID 15324458, 2004). "Finally, since Salmonella infection leads to an increase in pro-inflammatory TNF-α increase, we also tested whether this cytokine is affected by USP8 inhibition." (PMID 37026055, 2023). "These included the TNF signaling pathways, NOD‐like receptor signaling pathways, necroptosis, influenza A, NF‐kappa B signaling pathways, apoptosis, Escherichia coli infection, Salmonella infection, hepatitis C, pathogenic, and RIG‐like receptor signaling cascade." (PMID 36533709, 2023). "While induction of TNF-α with Salmonella infection in the ileum was significant, expression in the colon of the piglets previously colonized with both lactobacilli was reduced, suggesting that lactobacilli partially suppressed local expression of TNF-α in the colon." (PMID 31434337, 2019). "In this study, we used a murine model of systemic Salmonella infection to explore whether an anti-inflammatory/immunosuppressive treatment based on in vivo neutralization of TNFα would have a synergistic or detrimental effect on the course of treatment with ampicillin or ciprofloxacin." (PMID 28087648, 2017). "Thus, the network analysis is consistent with the previous experiment results: production of TNF-α in the intestinal tract following S. typhimurium infection and the observation that early pathology induced by Salmonella infection of the gastrointestinal tract is mediated by immune mechanisms." (PMID 21172007, 2010). "Therefore, further experiment is needed to establish whether this gene is up-regulated by TNF-α in mouse colonic mucosa after Salmonella infection." (PMID 21172007, 2010). "In response to Salmonella infection, elevated levels of pro- and anti-inflammatory cytokines, including IFN-γ, TNF-α, IL-17, and IL-10 have been detected in the placenta, amniotic fluid, and maternal serum." (PMID 40709995, 2025). "A network analysis identified an interaction between the Toll-like receptor pathway and Salmonella infection via TLR4 and TLR2, the NOD-like receptor pathway and Salmonella infection via GBP1, and the TNF signaling pathway and Salmonella infection via IRF1." (PMID 40005871, 2025). "Concomitantly, we investigated the regulatory effect of EcN preconditioning on the release level of tumor necrosis factor alpha (TNF-α)and interleukin-6 (IL-6) in host cells induced by Salmonella infection." (PMID 41181117, 2025). "The top five pathway terms associated with DEGs between the OGD/R and OGD groups were the TNF signaling pathway, TGF‐β signaling pathway, cytokine–cytokine receptor interaction, NOD‐like receptor signaling pathway, and Salmonella infection." (PMID 37789643, 2024). "Salmonella infection stimulates proinflammatory cytokines such as IFN-γ and TNF-α in both infected and adjacent cells." (PMID 39061933, 2024). "Compared with CON, plasma concentrations of IFN-β IL-8 (P < 0.01), IgG, IgA, IL-1β, TNF-α, and IFN-γ (P < 0.05) increased following Salmonella infection (SI)." (PMID 38053560, 2023). "Comparatively, when compared to WT mice, TNF-α, IL-6, and INF-γ of MafK Tg mice were increased significantly following Salmonella infection for 2 days in the colon." (PMID 35260530, 2022). "The host anti-tumor responses can be induced after Salmonella infection by recruiting immune cells, such as neutrophils, macrophages, dendritic cells and CD8+ T cells, and cytokines including IL-1β and TNF-α into tumor tissue." (PMID 35003007, 2021). "Primary Salmonella infection increases interferon gamma (IFN-γ), tumor necrosis factor alpha (TNF-α), and interleukin 12 (IL-12) in circulation and in local tissues." (PMID 31540475, 2019).
Salmonella Infections (continued). "Enriched KEGG pathways included “TNF signalling” (FDR 4.37x10-5), “Salmonella infection” (FDR 0.00407), “Chagas disease” (FDR 0.0078) and “Leishmaniasis” (FDR 0.0205)." (PMID 31976381, 2019). "In mouse peritoneal MΦs, Salmonella infection up-regulated the expression of both of M1 MΦ markers (CCR7 and CD86), M2 MΦ marker (CD163 and CD206) and induced the secretion of M1 MΦ marker TNF-α and M2 MΦ marker IL-10 in ascitic fluid significantly." (PMID 30271755, 2018). "At the early stage of Salmonella infection, the production of cytokines, such as interferon (IFN)-γ, interleukin (IL)-1β, IL-8, and tumor necrosis factor (TNF)-α, is of utmost importance for controlling Salmonella growth and spread in the host body." (PMID 28848530, 2017). "We observed that Salmonella counts, phagocytic cell (MDMI and MDMII) counts, and pro- and anti-inflammatory cytokine (TNF-α, HMGB-1 and IL-10) counts increased as Salmonella infection (load) increased." (PMID 27556404, 2016). "Earlier data from a murine model suggested a TNFα- and IL-1-mediated expression of ICAM-1 on hepatocytes following Salmonella infection." (PMID 24932686, 2014). "For example, ERK activation is involved in response to Salmonella infection of macrophages, and MAP kinase activation is required for tumor necrosis factor-α (TNF) production in response to Group B streptococcus infection." (PMID 19566962, 2009). "This profile is in sharp contrast to the immune responses induced in Salmonella infection where microbial control is highly dependent on type 1 (Th1) immunity, mainly marked by the production of interferon-gamma (IFN-γ), tumor necrosis factor-alpha (TNF-α) and IL-1212,13." (PMID 38918457, 2024). "Natural killer (NK) cells play a central role in immunity to Salmonella infections through the production of pro-inflammatory cytokines such as IFN-γ and TNF-α as well as by the release of granzyme B and perforin cytotoxic effector molecules leading to the killing of the infected host cells." (PMID 38918457, 2024). "Therefore, when the intestinal barrier function is destroyed upon salmonella infection, these pro-inflammatory cytokines, including IL-1β, IL-6, IL-8, IFN, and TNF-α, are activated." (PMID 35371085, 2022). "Cytokines such as tumor necrosis factor-alpha (TNF-α) and interferon-gamma (IFN-γ) produced by the cells of the innate immune system, such as dendritic cells, have antimicrobial activities and are also involved in control of Salmonella infection." (PMID 23989890, 2013). "The CD1b- L-DCs constitutively expressed GATA-3, TNF-α, IL-23 and IL-4 genes which were down-regulated after Salmonella infection, but not after stimulation with helminth secretions." (PMID 24223964, 2013). "Thus, polyfunctional CD4+ T cells that develop during Salmonella infection produce simultaneously IFN-γ, TNF and IL-2 and the differential amounts of IFN-γ that is being produced by these cells correlates with the immunodominance hierarchy." (PMID 22912884, 2012). "The level of cytokinemia during Salmonella infections does not reach the toxic levels seen in endotoxic shock, and inhibition of TNFα during Salmonella infection worsens the outcome." (PMID 19156198, 2009). "Moreover, KEGG pathway analysis suggested that 22 PRGs were mainly enriched in immune and cancer-related pathways, including the Helicobacter pylori and salmonella infection, Toll-like and NOD-like receptor signaling pathway, VEGF and TNF signaling pathway, drug resistance and apoptosis." (PMID 35937993, 2022).
Salmonella Infections (continued). "The interaction with these cells induces the synthesis of inflammatory cytokines, such as TNF-α and IFN-γ, leading to a massive influx of immature neutrophils, macrophages and DCs, which are necessary for the suppression of bacterial growth in intestinal lumen in Salmonella infections." (PMID 30564201, 2018). "Nevertheless, the S. Typhimurium “typhoid” mouse model has led to important insights into the role that various innate and adaptive effector mechanisms might play in protection from Salmonella infection, including production of interferon (IFN)-γ and tumor necrosis factor (TNF)-α by CD8+ T cells." (PMID 28303138, 2017). "Furthermore, ELISA analysis of cytokine concentration in spleen and liver homogenates confirmed that Salmonella infection induced a marked increase in production of TNF-α in spleen from mice lacking p40phox." (PMID 29062317, 2017). "Thus, immunodeficiency due to lack of TNFα does not preclude the possibility to treat a systemic Salmonella infection." (PMID 28087648, 2017). "Thus, simultaneous administration of antibiotics and anti-TNFα treatments during an established systemic Salmonella infection neither impairs nor enhances the rate at which antibiotics reduce bacterial numbers in the infected tissues." (PMID 28087648, 2017). "In the presence of functional IL-12, the loss of IL-23 may not affect susceptibility to Salmonella infection due to enhanced IFN-γ production and accumulation of TNF and Nos2 producing cells." (PMID 22624013, 2012).
lung disease (152 papers, 2005 to 2026). "Accumulating data suggest that TNFα is essential in the pathogenesis of AATD-associated lung diseases." (PMID 40013145, 2025). "The concentration of TNFα is significantly higher in patients with COPD, and TNFα is essential in the pathogenesis of lung diseases associated with AATD." (PMID 40013145, 2025). "In particular, more caution should be taken when prescribing anti-TNF to RA patients, especially older patients with a more extended RA history or RA-associated pulmonary disease." (PMID 37175894, 2023). "High levels of IL-6 and TNF-α have been associated with worse prognosis and higher mortality rate in patients with lung disease." (PMID 35745755, 2022). "Both TNF-a and IL-6 have been shown to be independent risk factors of increased morbidity and mortality in hypoxic lung disease, particularly in COPD." (PMID 35634304, 2022). "Our Cox multivariate analysis adjusted for follow-up time showed that non–anti-TNF bDMARDs were associated with a lower risk of progression of lung disease and mortality." (PMID 33672699, 2021). "Among bDMARDs, anti-TNF agents were associated with risk of progression, while the non-anti-TNF bDMARDs are associated with a reduced risk of progression of lung disease." (PMID 33672699, 2021). "It seems unlikely that the increased levels of TNF-alpha in MZ heterozygotes were caused by unrecognized inflammatory lung impairment since none of the MZ heterozygotes suffered from clinically significant lung disease." (PMID 34638908, 2021). "TNF-α has also been implicated in a variety of pulmonary diseases and plays a crucial role in the occurrence and development of lung injury and fibrosis." (PMID 33072088, 2020). "Using a mouse line with lung-specific Tnf-α overexpression (SPC-TNF-α) to mimic TNF-α-associated lung diseases, we investigated the role of chronic inflammation in the homeostasis of lung trace elements." (PMID 27378943, 2016). "Specifically, TNFα is thought to be involved in several chronic hypoxia-associated lung diseases like COPD." (PMID 27441378, 2016). "Multifunctional CD4+ Th1 cells, co-expressing IFN-γ/TNF-α/IL-2 or IFN-γ/IL-2 or IFN-γ/TNF-α have been shown to be associated with protection against active pulmonary disease in TB." (PMID 25211342, 2014). "It has been also demonstrated that certain TNFα polymorphisms, other than −308 G/A polymorphic loci, are also associated with severity of CF lung disease in Czech and Belgian patients." (PMID 23343370, 2013). "The inflammatory response in lung disorders is characterized by high levels of TNF-α, which attracts neutrophils to the lung, thereby causing the excessive release of HNE." (PMID 24376583, 2013). "As an anti-inflammatory agent in association with lung diseases curcumin inhibited pro-inflammatory cytokines including IL-8, IL-1, and TNF through the inhibition of the transcription factors NFκB and AP-1." (PMID 23437361, 2013). "The inflammatory mediators implicated in lung disease, including C-reactive protein, fibrinogen, activated complement components, and cytokines (e.g., interleukin 6, interleukin 1, tumor necrosis factor-α) have also been associated with the development of AF." (PMID 23118762, 2012). "TNF-α is considered to be a key inflammatory mediator in lung pathology, and its levels are elevated in lung diseases where LPS is implicated and neutrophilic inflammation is prominent." (PMID 22412999, 2012). "We aimed to determine whether complement deficiency is protective against joint and lung disease using the tumor necrosis factor-transgenic (TNF-Tg) mouse model characterized by chronic inflammatory-erosive arthritis and PH." (PMID 41642804, 2026). "CF-related airway inflammation is also associated with heightened production of pro-inflammatory cytokines such as tumor necrosis factor (TNF-α) and interleukin (IL)−1β, IL-6, and IL-8, which are closely linked to lung disease progression and reduced survival in PwCF." (PMID 39475317, 2024).
lung disease (continued). "NTM are opportunistic in their infectious processes, making immunocompromised individuals such as those with other systemic infections such as HIV, immunodeficiencies, pulmonary disease, or usage of medications such as long-term corticosteroids/TNF-α inhibitors more susceptible." (PMID 35335022, 2022). "Mycobacterium avium is an environmental pathogen that causes opportunistic infection in people with underlying lung disease or that are immunocompromised, e.g., from immunosuppressive treatment, such as neutralization of tumor necrosis factor alpha (TNF-α) (1, –, 3)." (PMID 34607464, 2021). "TNFα has been suggested to be essential in the pathogenesis of lung diseases associated with AATD." (PMID 33329539, 2020). "Indeed, TNFα signaling has been proposed to drive immune cell dysfunction causing lung diseases in AATD individuals." (PMID 33329539, 2020). "The high concentration of TNF-α in smokers is understood to reflect smoke-induced lung injuries and is considered a useful biomarker for the identification of heavy smokers with a high risk of developing smoke-induced pulmonary diseases." (PMID 27274336, 2016). "Thus, high level generation of TNFα is linked to the pathophysiological consequences in a number of pulmonary diseases." (PMID 17034639, 2006). "Glycolytic-driven activation of immune cells might contribute to epithelial damage in pulmonary diseases, for example via released cytokines such as tumor necrosis factor (TNF), causing loosening of tight junction and cell death, which can be defined as a metabolic-driven injury." (PMID 38550597, 2024). "Moreover, TNF-α may upregulate goblet cell hyperplasia, which has been implicated in a number of lung diseases." (PMID 35163689, 2022). "Additional host factors associated with NTM lung disease include gastroesophageal reflux, advanced age, thin body habitus often with thoracic cage abnormalities such as scoliosis and pectus excavatum, and the use of inhaled corticosteroids and anti-tumor necrosis factor-alpha (anti-TNF-α) therapies." (PMID 33207695, 2020). "This approach offers a promising imaging tool for patient stratification, therapy monitoring, and guiding anti-TNF interventions in pulmonary diseases." (PMID 42095068, 2026). "TNFα is a potent pro-inflammatory cytokine involved in several pulmonary disorders such as IPF; it led to an increase in IL-6 expression in both cell types." (PMID 41155824, 2025). "TNF‐α contributes to the initiation and progression of inflammation, oxidative stress, and cytotoxic cellular injuries in lung diseases." (PMID 40330764, 2025). "We also assessed the association of cavitary lung disease and other measures of bacillary burden with IFN-γ, IL-2, and TNF responses in HHCs." (PMID 39606489, 2024). "IL-6 and TNF-α were investigated due to being prevalent in pulmonary diseases and as a result of long-term vaping." (PMID 38339063, 2024). "In animal models of pulmonary disease, eugenol was shown to have anti-inflammatory effects, as measured by a reduction in both TNF- and neutrophil infiltration." (PMID 36770859, 2023). "Further studies are needed to clarify the uncertain role of TNF-α inhibitors in lung disorders and help treatment decisions." (PMID 37175894, 2023). "Eugenol displayed a decrease in inflammation of reducing TNF-α and neutrophil infiltration during pulmonary disease in animals." (PMID 36770859, 2023). "TNF-α has been recognized as systemic inflammatory molecules acting synchronously on lung parenchyma and the skeletal muscle in lung disease, is a key cytokine in the regulation of muscle mass signaling via a number of pathways." (PMID 35903456, 2022). "Tumor Necrosis Factor alpha (TNFα) is a potent cytokine that can lead to the exacerbation of inflammatory responses with significant roles in many diseases, including pulmonary disorders." (PMID 35741013, 2022). "MIF controlled the production of other cytokines such as IL-1β, IL-6, IL-8 and TNF-α in neonatal lung diseases." (PMID 33356032, 2021).